CD33 (CD33 molecule)
Diseases named in the same sentence as CD33 in open-access papers (continued):
Sharing a sentence is not in itself a finding about the gene and the disease.
melanoma (continued). "We also examined a separate cohort of melanoma patients and found a similar elevation of CD14+CD33+ monocytes in patients responsive to PD-1 blockade." (PMID 35493454, 2022). "Here, using a transplantable model of human melanoma in humanized mice, we find that CD117+CD11b+CD33+ myeloid cells support melanoma growth in distant organs." (PMID 33857287, 2021). "PBMC cultures in the presence of melanoma cells also showed an increased percentage of CD1c+ DCs (CD33+CD14−HLA-DR+CD1c+) among leukocytes, with a trend toward melphalan-exposed melanoma cells inducing the highest expansion of DCs." (PMID 30560089, 2018). "PBMC collected from the peripheral blood of melanoma patients and pancreatic adenocarcinoma patients were phenotyped for MDSC using the cell surface markers HLA-DR, CD33, CD11b (30,000 events) and the production of NO was measured using the DAF-FM stain." (PMID 29133913, 2017). "First, we analyzed CD33dimHLA-DRlow/−CD66b+Lin− PMN- and CD33+HLA-DRlow/−CD14+ M-MDSC in PBMC from melanoma patients and their non-suppressive MDSC counterparts from HD by flow cytometry." (PMID 36860876, 2023). "CD33 was also significantly upregulated in cells treated with A-366 (p < 0.0001), further demonstrating that it is regulated by H3K9 methylation in melanoma." (PMID 35223844, 2022). "Thus, CD33 enriched on monocytes is predictive of positive anti-PD1 responses in both NSCLC and melanoma." (PMID 35493454, 2022). "Moreover, IFNγ signatures (CXCL10, CXCL9, IDO1, IFNG, and STAT1) and myeloid lineage phenotypic and functional markers (CD14, CD163, CD33, and CD68) were also significantly increased in melanoma patients with high ETV7." (PMID 33424867, 2020). "In conclusion, our study suggests that studies on the expression of CD33 and VISTA in melanoma may be of pivotal future interest." (PMID 32873829, 2020). "As observed in patients undergoing M-ILP, the melphalan-exposed melanoma cells also triggered an increased proportion of CD33+CD14+CD16++ non-classical monocytes in vitro." (PMID 30560089, 2018). "Moreover, when the melphalan-treated melanoma cells were co-cultured with PBMCs, this triggered an increased proportion of CD33+CD14+CD16++ non-classical monocytes among the PBMCs." (PMID 30560089, 2018).
multiple myeloma (18 papers, 2012 to 2023). "This implicated CD33+ myeloma associated with poorly differentiated neoplastic plasma cell type." (PMID 24991573, 2014). "It should be noted that RPMI8226 cells, which were derived from a multiple myeloma, expressed an appreciable amount of CD33 as previously reported." (PMID 27233074, 2016). "However, by CSC profiling, CD33 shows low mass spectrometric intensity on myeloma plasma cells, suggestive of low surface protein expression." (PMID 35840578, 2022). "Therefore, exploiting CD33 upregulation on lenalidomide-resistant myeloma may prove challenging." (PMID 35840578, 2022). "Multiple myeloma cells express other cell-surface tumor antigens that can be targeted, such as CS1, CD38, and CD33." (PMID 30208593, 2018). "The expression status of CD13, CD19, CD20, CD33, CD38, CD56, and CD117 was analyzed on myeloma cells from 55 newly diagnosed patients, including 36 men (65%), of median age 61 years (range: 38–78)." (PMID 24991573, 2014). "In myeloma models we identify proteins that could serve as markers of resistance to bortezomib and lenalidomide, including CD53, CD10, EVI2B, and CD33." (PMID 35840578, 2022). "For mechanism of CD13 and CD33 in myeloma cells, there was no suggested pathway." (PMID 24991573, 2014). "For example, CD33 and SLAF7, together with CD38 (which did not have plasma pQTL data), are targeted by mAbs for multiple myeloma." (PMID 37126556, 2023).
acute promyelocytic leukemia (16 papers, 2010 to 2024). An aggressive form of acute myeloid leukemia (AML), characterized by arrest of leukocyte differentiation at the promyelocyte stage, due to a specific chromosomal translocation t(15;17) in myeloid cells. "CD33 is associated with a number of diseases, including acute leukemia and acute promyelocytic leukemia." (PMID 34622712, 2021). "CD33 is highly expressed in acute promyelocytic leukemia (APL), NPM1-mutated AML, and FLT3/ITD mutated AML, whereas expression is usually low in leukemias with core-binding factor translocations." (PMID 36276074, 2022). "The CD33 expression level appears linked to the differentiation status of the leukemia clone (e.g., high level is seen in acute promyelocytic leukemia; APL), the cytogenic profiles and to certain mutations, such as NPM1 and FLT3/ITD." (PMID 35690610, 2022). "As a second xenograft tumor model to evaluate DARIC-VHH antitumor activity, we used the CD33-expressing acute promyelocytic leukemia-like cell line HL-60, modified for BLI." (PMID 38502193, 2024). "CD33 expression is essentially universal in acute promyelocytic leukemia (APL), with cells typically surrounded by large amounts (95–100%) of the antigen." (PMID 34203180, 2021). "The excellent efficacy of gemtuzumab ozogamicin in acute promyelocytic leukemia (Breccia and Lo‐Coco, 2011) which is CD33‐dense suggests that the therapeutic window is likely to be widest when AML subtypes are chosen with high receptor levels." (PMID 31338922, 2019). "In acute promyelocytic leukemia (APL) patients, tumor-activated ILC2s secreted IL-13 to induce M-MDSCs (CD33+CD14+HLA-DR-) and to support tumor growth, while ATRA treatment reversed the increase of ILC2-MDSCs in APL." (PMID 31640764, 2019). "In acute promyelocytic leukemia (APL) patients, peripheral ‘group 2 innate lymphoid cells’ (ILC2s) were found to be increased and hyperactivated, and in turn activated M-MDSC (CD14+CD33+) through IL-13 secretion." (PMID 36304465, 2022). "CD33 is expressed in approximately 85–90% of adult and child AML patients and in 100% of acute promyelocytic leukemia (APL), which is a subset of AML." (PMID 25339341, 2015). "GO was also approved by the European Medicines Agency (EMA) in February 2018 in combination therapy with DNR and AraC for the treatment of patients ≥ 15 years old with previously untreated, de novo CD33 + AML, except acute promyelocytic leukemia (APL)." (PMID 33059764, 2020). "In 2018, Mylotarg was approved by the European Medicines Agency (EMA) for the treatment of patients aged 15 years and above affected by de novo CD33-positive AML, except acute promyelocytic leukemia (APL), in combination with daunorubicin (DNR) and cytarabine (AraC)." (PMID 36642712, 2023). "The typical phenotype of acute promyelocytic leukemia (APL) is myeloperoxidase positive and CD33 positive, human leukocyte antigen (HLA)-DR negative." (PMID 21547051, 2010).
amyloid (15 papers, 2015 to 2025). "Notably, CD33, a top AD risk gene linked to microglial function that was identified through genome‐wide association studies, was upregulated in plasma in amyloid‐positive subjects." (PMID 39689057, 2025). "The study proposes that over time, the CD33-R69G variant, which binds to sialic acid, could boost CD33’s ability to inhibit the breakdown of amyloid plaques." (PMID 39651329, 2024). "Moreover, CD33 protein is elevated in AD brain and has been associated with amyloid pathology and disease progression." (PMID 28612290, 2017). "Still, the several studies showing different effects of CD33 in AD, such as an elevated expression in AD brain associated with amyloid pathology, disease progression, and microglial activation may reflect the important role of CD33 biological pathway in AD, most likely dependent on TREM227." (PMID 35589863, 2022). "Specifically, we find that the interaction of CD33 and PTPN6 modulates the association with amyloid burden, tangles, pathological diagnosis of AD, and global burden of AD pathology." (PMID 39336795, 2024). "This type of comprehensive studies are crucial to continue disentangling the beneficial (or detrimental) role(s) of TREM2 and CD33, and respective intracellular signalling pathways, in murine models of amyloidosis, tauopathy, or mixed pathologies." (PMID 37580702, 2023). "It was already demonstrated that knocking out CD33 results in lower Aβ levels and reduced amyloid plaque burden in the brain of APP(Swe)/PS1(ΔE9)/CD33KO mice." (PMID 35327591, 2022). "CD33 is upregulated in the AD brain and is positively correlated with disease severity, while knockout mice have been shown to have reduced amyloid plaque formation." (PMID 34857772, 2021). "CD33-deficient Amyloid precursor protein (APP)/Presenilin 1 (PS1) mice showed reduced amyloid pathology compared to age-matched wildtype (WT) controls, supporting the idea that reduced microglial CD33 function is beneficial with respect to amyloid pathology." (PMID 31507408, 2019). "Accordingly, in the cortex of AD patients, a positive correlation of microglial CD33 expression and amyloid pathology was described, indicating that increased CD33 expression in microglia promotes plaque pathology." (PMID 31507408, 2019). "We address this challenge by studying transgenic mice expressing either of the human CD33 isoforms crossed with the 5XFAD mouse model of amyloidosis and find that human CD33 isoforms have opposing effects on the response of microglia to amyloid-β (Aβ) deposition." (PMID 38802940, 2024). "We propose that this change in binding enhanced the inhibitory effects of CD33 on amyloid plaque degradation, and together with other genetic, epigenetic, and environmental factors, could predispose to the accumulation of amyloid plaques and the onset of AD pathology." (PMID 35408990, 2022). "Genetic variants of genes such as CD33 and TREM2 have been shown to alter (increase or decrease) the phagocytic functions of microglia and thus may directly (or indirectly) contribute to tau pathology, independent of their potential effects on amyloid pathology." (PMID 26057852, 2015). "One of these studies also described the effects of CD33-knockout in the APP/PS1 mouse model, in demonstrating that APP/PS1-CD33−/− mice displayed a significant decrease in amyloid plaque burden, without altering APP processing, compared to APP/PS1-CD33+/+ controls." (PMID 30249283, 2018).
acute leukemia (14 papers, 2012 to 2025). A clonal (malignant) hematopoietic disorder with an acute onset, affecting the bone marrow and the peripheral blood. "In 24-hour assays, we found some differences between individual CD33 variants in several acute leukemia cell lines; however, while highly reproducible, these differences were not consistent across cell lines but, rather, appeared cell context specific." (PMID 27248327, 2016). "In acute leukemia cell sublines engineered to express individual CD33 splice variants, all splice variants had endocytic properties." (PMID 27248327, 2016). "Our studies in lentivirally-transduced acute leukemia cell lines also show that the CD33 variants that contain exon 7a, and therefore lack almost the entire cytoplasmic tail of CD33, are internalized." (PMID 27248327, 2016). "Similar to wild-type CD33, our experiments in engineered acute leukemia cell lines document that the CD33∆E2 variant is internalized, and could thus also serve as target for CD33-directed therapeutics that depend on intracellular delivery of a toxic payload." (PMID 27248327, 2016). "We used a large panel of parental and CD33-engineered human acute leukemia cells to characterize the in vitro activity of CC-96191 with KHYG-1CD16a cells." (PMID 38473239, 2024). "To investigate the potential role of the fully humanized bispecific antibody CD16 × CD33 (BiKE) in children with CD33+ acute leukemia, we tested whether the reagent was able to boost NK cell effector functions against CD33+ AML and biphenotypic ALL blasts." (PMID 34398302, 2021). "Flow cytometry of bone marrow biopsy revealed an immature (blast) cell population expressing CD5, CD34, and CD38, highly suggestive of acute leukemia, particularly AML, given the co-expression of CD13 and CD33 found in peripheral blood." (PMID 40978971, 2025). "Flow cytometry data indicated that the markers CD34, CD33, CD13, and CD7 were common in SET-CAN/NUP214 positive acute leukemia, including ALL." (PMID 35905214, 2022). "Similarly, the diagnosis of acute leukemia was confirmed by identifying over 20% blasts in the bone marrow, which were characterized as myeloid in origin by positive CD13, CD33, and MPO markers on flow cytometry." (PMID 39619312, 2024). "We firstly reported EP300-ZNF384 fusion in a mixed-phenotype acute leukemia (MPAL) patient whose CD33 and CD13 were negative." (PMID 32980888, 2020). "Acute leukemias with co-expression of CD19 and CD33 usually have a poor prognosis." (PMID 26981773, 2016). "In acute leukemia of ambiguous origin with B/myeloid or trilineage phenotype (ca. 2 – 3% of all acute leukemias) and B-ALL or AML with aberrant antigen expression, the B lymphoid lineage marker CD19 and myeloid lineage marker CD33 are simultaneously displayed on the blast cell surface." (PMID 26981773, 2016). "We demonstrated that primary acute leukemia cells were sensitive to α-bisabolol at concentrations that did not affect their normal counterpart (i.e. normal CD34+ and CD33+ myeloid cells)." (PMID 23056396, 2012).
cognitive decline (14 papers, 2012 to 2025). "For instance, late-stage AD is characterized by increased expression of TREM2 and CD33, two genes involved in microglial activation and inflammation, correlating with rapid cognitive decline and neuronal loss." (PMID 40004464, 2025). "CD33 is found to inhibit the microglial uptake and clearance of Aβ, and CD33 levels are increased in the AD brain and associated with greater cognitive decline." (PMID 39219300, 2025). "Previous studies have found that higher CD33 expression in the parietal lobe is associated with more advanced cognitive decline or disease status, and knocking out CD33 results in lower Aβ levels and reduced amyloid plaque burden in the brain." (PMID 36192375, 2022). "Genotyping of selected single-nucleotide polymorphisms in the APOE, ABCA7, SORL1, BIN1, GAB2, and CD33 genes was conducted, and a Bayesian hierarchical model was fitted to analyze the trajectories of cognitive decline among different genotypes." (PMID 34214049, 2021). "The C allele of CD33 (rs3865444) has been associated with an increased risk of AD in genome-wide association studies, has been tied to more severe cognitive decline in AD, and correlated with lower MMSE scores." (PMID 26102276, 2015). "In addition, CD33-positive microglia and CD33 protein levels were found to be increased in AD brains, and CD33 was found to be associated with cognitive decline." (PMID 33324164, 2020). "There is evidence that higher expression of CD33 in brains is associated with cognitive decline." (PMID 29177109, 2017). "Among those with one or more APOE ε4 alleles, having one or more copies of the CD33 C (risk) allele may further increase the risk of cognitive decline." (PMID 26102276, 2015). "AD brains show higher levels of CD33 on their microglia, and CD33 presence is correlated with plaque burden and cognitive decline." (PMID 39456461, 2024). "We found that ABCA7, CD33, and CR1 expression levels were associated with clinical dementia rating (CDR), with higher expression being associated with more advanced cognitive decline." (PMID 23226438, 2012).
COVID-19 (14 papers, 2020 to 2025). A disease caused by infection with severe acute respiratory syndrome coronavirus 2. "In sepsis and COVID-19, excessive activation of CD33 + myeloid cells triggered abnormal inflammation responses, thus resulting in immunosuppression, which represented typical pathogenesis of these two diseases." (PMID 41411324, 2025). "Transcriptomic analyses of PBMCs from patients with acute COVID-19 showed that upregulated genes were enriched in bone marrow, blood CD33+ myeloid cells, and CD14+ monocytes." (PMID 39205185, 2024). "This analysis indicates the relevant role of several markers such as TMPRSS2, CD45-, CD163/CD206, and CD33 for COVID-19 aggressiveness." (PMID 36969980, 2022). "Here, we report the interesting role of TMPRSS2, CD45-, CD163/CD206, and CD33 in COVID-19 aggressiveness." (PMID 36969980, 2022). "This is a pioneer study, which correlates the frequency of both CD33+CD11b+HLA-DR-CD14+ cells and CD33+CD11b+HLA-DR-CD66b+ cells to COVID-19 severity, as previous reports only highlighter the expansion of polymorphonuclear MDSC." (PMID 33178720, 2020). "Leukocytes levels expressing the myeloid marker CD33 were increased in COVID-19 patients." (PMID 35625671, 2022). "In addition, we found that CD14dim/CD33+ are good options as biomarkers for stratification of mild/severe COVID-19." (PMID 36969980, 2022). "To explore whether the monocytes from COVID-19 patients exhibit a similar phenotype, we evaluated the expression levels of several activation markers, including CD33, CD86, CD80, HLA-DR, and CD40, in monocytes isolated from the peripheral blood mononuclear cells (PBMCs) of HD, MP and SP group." (PMID 39996729, 2025). "As shown in this distribution map, the top 4 tissues or cells with highest target gene expressions were CD33 + Myeloid, smooth muscle, fetal lung, and bronchial epithelial cells, respectively, which might play an important role in the treatment of both sepsis and COVID-19." (PMID 41411324, 2025). "When compared to HC, monocytes from acute COVID-19 patients had higher size (FSC) and granularity (SSC), higher expression of CD11b, CD16 and CD33, similar expression of CCR2, CCR5 and CD86, and a marked downregulation of HLA-DR, as previously reported." (PMID 34572439, 2021). "When compared to acute COVID-19 monocytes, the expression of CD16 and CD33 in post-COVID-19 monocytes was downregulated, equaling the level found in HC monocytes in the case of CD16." (PMID 34572439, 2021). "We hereby describe the possible novel severity biomarkers for COVID-19, CD11b+CD33+HLA-DR-CD14+ cells and CD11b+CD33+HLA-DR-CD66b+ cells." (PMID 33178720, 2020). "Overall, these findings suggest a correlation between the quantification of CD33+CD11b+HLA-DR-CD14+ cells and CD33+CD11b+HLA-DR-CD66b+ cells and the severity of COVID-19." (PMID 33178720, 2020). "Similarly, it has been previously reported that upregulation of C-Mo and, in particular, higher numbers of CD14+ CD33+ HLA-DR cells and S100A8/9/12 expressing C-Mo are present in severe/critical COVID-19 and sepsis." (PMID 36969980, 2022). "In addition, CD15 expression was most prominent in COVID-19 patients, particularly in severe cases, but when selecting for CD3− or CD3− CD33+ cells, convalescent patients possessed a number of CD15+ cells more similar to patients with active disease than healthy donors." (PMID 33361110, 2021). "Enhanced CD33+CD11b+HLA-DR–CD14–CD66b+ and CD33+CD11b+HLA-DR–CD14+CD66b– cells in the blood of ICU patients, classified as severe COVID patients, could represent not only a predictor of prognosis for COVID-19, but also specific therapy targets for treating this virus infection in the near future." (PMID 33178720, 2020). "At the admission time, we found a higher frequency of the PMN-MDSC cell population (identified as Lin−, HLA-DR−, CD11b+, CD33+, CD15+, CD14−) in 128 hospitalized COVID-19 patients requiring or not requiring intensive care unit (ICU) compared to HD." (PMID 33110074, 2020).